DAPL1 (death associated protein like 1)
Description:
May play a role in the early stages of epithelial differentiation or in apoptosis.
Tractability: No criterion of Open Targets' tractability assessment is met for any kind of drug.
Gene: Protein-coding gene on chromosome 2 (158,795,317 to 158,862,781, forward strand). Ensembl gene ENSG00000163331.
Subcellular location (Human Protein Atlas): Microtubules; Nuclear bodies; Nucleoplasm
Gene Ontology:
Molecular function: protein binding; ribosome binding; translation initiation factor binding; translation repressor activity
Biological process: apoptotic signaling pathway; negative regulation of autophagy; negative regulation of CD8-positive, alpha-beta T cell activation; ribosome hibernation
Cellular component: nucleus
Genetic constraint (gnomAD): Loss-of-function variants: 5 observed, 4.75 expected, observed/expected ratio (o/e) 1.05, 90% interval 0.54 to 1.83. That is too few expected variants to judge how well the gene tolerates losing a copy. Missense variants: 93 observed, 67.56 expected, observed/expected ratio (o/e) 1.38, 90% interval 1.16 to 1.63. Synonymous variants: 29 observed, 24.35 expected, observed/expected ratio (o/e) 1.19, 90% interval 0.89 to 1.62.
Homologues: Orthologues: macaque DAPL1 (97% identical), pig DAPL1 (87% identical), guinea pig DAPL1 (86% identical), mouse Dapl1 (81% identical), rat Dapl1 (81% identical), dog DAPL1 (80% identical), tropical clawed frog dapl1 (51% identical), zebrafish dap1b (40% identical), Drosophila melanogaster CG12384 (31% identical), Caenorhabditis elegans F54B8.4 (26% identical), Caenorhabditis elegans T28F4.5 (25% identical). Paralogues in human: DAP (33% identical).
Diseases named in the same sentence as DAPL1 in open-access papers:
DAPL1 is named in the same sentence as 38 diseases in open-access papers, as found by Europe PMC text mining. Sharing a sentence is not in itself a finding about the gene and the disease. The quoted sentences say what the papers report.
age-related macular degeneration (3 papers, 2015 to 2025). Age-related loss of vision in the central portion of the retina (macula), secondary to retinal degeneration. "More recently, additional functions of DAPL1 have been identified, including roles in T cell immunity, mRNA translational inhibition, and age-related macular degeneration (AMD), a leading cause of irreversible blinding disease in the aged population." (PMID 38980592, 2025). "Death-associated protein-like 1 (DAPL1, also known as early epithelial differentiation-associated protein, EEDA) is expressed in epithelial cells, and its genetic variant is associated with age-related macular degeneration (AMD)." (PMID 36841807, 2023).
breast carcinoma (2 papers, 2015 to 2021). "Potential oncogenes amplified in the breast cancer include GREB1, NRXN1, MGAT5, PKP4, DAPL1, ITGB6, and RBMS1, which may be implicated in carcinogenesis, proliferation, and invasion." (PMID 26432421, 2015).
endometritis (2 papers, 2020 to 2021). An acute or chronic, usually bacterial infectious process affecting the endometrium. "The expression patterns of only 28 genes in subclinical endometritis have been substantially altered, of which 26 genes including PTHLH, INHBA, DAPL1, MAOB, CXCR4, and TGIF1 were identified in both subclinical and clinical endometritis." (PMID 33426032, 2020). "There are 92 genes, including PTHLH, INHBA, DAPL1, and SERPINA1, which were significantly highly regulated and 111 genes which had significantly poorly regulated expression levels, including MAOB, CXCR4, HSD11B, and BOLA, as recorded in clinical endometritis." (PMID 33426032, 2020).
adenoma (1 paper, 2020). A neoplasm arising from the epithelium. "Interestingly, CYP3A5 together with CALB1, DAPL1 and FZD9 were recently reported to be enriched in human ACTH-secreting adenomas compared to other pituitary adenomas." (PMID 32183012, 2020).
cervical cancer (1 paper, 2022). A primary or metastatic malignant neoplasm involving the cervix. "In the present study, the immune subtype-relevant signature (covering TMEM125, TFF1, DECR2, LONRF3, DAPL1, and ANKRD35) was quantified, which predicted cervical cancer recurrence accurately and independently." (PMID 36313466, 2022).
Down syndrome (1 paper, 2023). "DAPL1 has been identified as a significantly differentially methylated region (DMR) in a 2021 study comparing DNAm in peripheral blood cells of toddlers with Down syndrome to neurotypical toddlers." (PMID 36855151, 2023).
exophthalmos (1 paper, 2025). "Subretinal injection of MuM-2C + DAPL1 + shP21 cells caused obvious exophthalmos, consistent with a large tumor volume in the eye." (PMID 38980592, 2025).
hepatoblastoma (1 paper, 2016). Hepatoblastoma (HB) is a malignant hepatic tumor and is the most common pediatric liver cancer. "However, the post-translational modifications regulated by GalNAcT5 in hepatoblastoma cells remain undefined, as the mechanism of action of DAPL1, ERMN, GALNT5, SCN1A and SCN3A genes." (PMID 27322213, 2016). "Cytogenetic data of hepatoblastoma have revealed that up-regulation of GALNT5, DAPL1, ERMN, SCN1A and SCN3A plays a major role in the development and progression of the disease." (PMID 27322213, 2016).
lentivirus infection (1 paper, 2025). Virus diseases caused by the Lentivirus genus. "To evaluate the role of DAPL1 in melanoma cells, we overexpressed DAPL1 in A375, C918 and MuM-2C melanoma cell lines by lentivirus infection." (PMID 38980592, 2025).
lung carcinoma (1 paper, 2025). "Hypomethylation of DAPL1 also is associated with the prognosis of the EGFR Del19 mutation subtype in lung cancer patients, and lung cancer patients showing hypomethylation of DAPL1 have significantly longer overall survival times." (PMID 38980592, 2025).
melanoma (1 paper, 2025). A malignant, usually aggressive tumor composed of atypical, neoplastic melanocytes. "We also performed examined the effects of loss of DAPL1 function on the proliferation of melanoma cells through siRNA-mediated DAPL1 knockdown." (PMID 38980592, 2025). "Here, we show that death-associated protein-like 1 (DAPL1) expression is lower in melanoma tissues than in paracancerous tissues or nevus tissues, and Uveal melanoma patients with lower DAPL1 expression have a poorer survival rate than those with higher expression of DAPL1." (PMID 38980592, 2025). "In the present study, we show that DAPL1 expression in melanoma is low relative to that in paracancerous tissues and nevus tissues." (PMID 38980592, 2025). "In summary, our study reveals a novel mechanism in which DAPL1 acts as a tumor suppressor by inhibiting the proliferation of melanoma cells by increasing P21 protein stability." (PMID 38980592, 2025). "However, the biological function of DAPL1 in melanoma and the underlying mechanisms remain unclear." (PMID 38980592, 2025). "Overexpression of DAPL1 inhibits proliferation of cultured melanoma cells, whereas knockdown of DAPL1 increases cell proliferation." (PMID 38980592, 2025). "Knockdown of P21 neutralizes the inhibition of melanoma cell proliferation by DAPL1 in vitro and enhances the severity of melanoma tumorigenesis in nude mice in vivo." (PMID 38980592, 2025). "Tumor transplantation experiment results also demonstrate that DAPL1 inhibits tumorigenesis of melanoma cells both in subretinal and subcutaneous tissues of nude mice in vivo." (PMID 38980592, 2025). "Clarification of the precise mechanisms of DAPL1 in melanoma tumorigenesis will deepen our understanding of the pathogenesis of melanoma and potentially provide an actionable therapeutic strategy, which needs to be addressed in future work." (PMID 38980592, 2025). "To confirm this result, we also analyzed the mRNA levels of P21 in melanoma cells overexpressing DAPL1." (PMID 38980592, 2025). "In this study, we used bioinformatics analysis, cellular and biochemical investigations, and a nude mouse model, all of which consistently support the role of DAPL1 as a novel melanoma suppressor gene." (PMID 38980592, 2025). "Fourth, DAPL1 decreases turnover of P21 in melanoma cells, and knockdown of P21 neutralizes inhibition of melanoma cell proliferation by DAPL1." (PMID 38980592, 2025). "Pathological analysis of eye tissue sections showed that the average tumor size of the DAPL1-overexpressing melanoma cells was significantly smaller than the EGFP control UM cells." (PMID 38980592, 2025). "Overexpression of DAPL1 in melanoma cells inhibits cell proliferation in vitro and tumor growth in vivo." (PMID 38980592, 2025). "Mechanistically, DAPL1 inhibits ubiquitination mediated degradation of P21 and promotes its stability, inhibiting the proliferation of melanoma cells." (PMID 38980592, 2025). "To clarify this, we further investigated the effect of DAPL1 on melanoma tumorigenesis in 6-week-old BALB/c male nude mice." (PMID 38980592, 2025). "Here, we show that DAPL1 acts as a novel P21 ubiquitylation regulator in melanoma cells, which deepens our understanding of this process." (PMID 38980592, 2025). "Here we further show that DAPL1 regulates melanoma tumorigenesis, suggesting that DAPL1 has multiple critical biological functions." (PMID 38980592, 2025). "Conversely, knockdown of P21 neutralizes the effects of inhibition of DAPL1 on melanoma cell proliferation and enhances the severity of melanoma tumorigenesis." (PMID 38980592, 2025). "Third, overexpression of DAPL1 inhibits melanoma cell proliferation in culture and inhibits melanoma tumor growth in nude mice." (PMID 38980592, 2025). "To determine whether P21 mediates DAPL1 inhibition of melanoma tumor growth, we constructed a shRNA lentivirus targeting P21 (shP21) to knock down P21 in A375 + DAPL1 and MuM-2C + DAPL1 cells." (PMID 38980592, 2025).
melanoma (continued). "Thus, overexpression of DAPL1 inhibits melanoma cell proliferation, while knockdown of DAPL1 increases melanoma cell proliferation in cultured melanoma cells." (PMID 38980592, 2025). "Conversely, knockdown of DAPL1 in melanoma cells increases cell proliferation." (PMID 38980592, 2025). "Pathological analysis of eye tissue sections showed significantly more extensive tumor sizes with MuM-2C + DAPL1 + shP21 melanoma compared to MuM-2C + DAPL1 + shNC mice, indicating that knockdown of P21 attenuates the inhibitory effect of DAPL1 on melanoma tumor growth." (PMID 38980592, 2025). "DAPL1 increases P21 protein levels in melanoma cells and promotes its nuclear localization." (PMID 38980592, 2025). "Finally, DAPL1 inhibits proliferation of melanoma cells by increasing the protein level of P21 via decreasing the ubiquitin mediated degradation of P21 and promoting its stability." (PMID 38980592, 2025). "Taken together, all these results suggest that DAPL1 inhibits the proliferation of melanoma cells." (PMID 38980592, 2025). "Thus, besides the results presented this work, the complex functional roles of DAPL1 in melanoma tumorigenesis might include immunity and inflammation among others." (PMID 38980592, 2025). "Moreover, we also revealed that DAPL1 exists in a positive feedback loop with microphthalmia-associated transcription factor (MITF), which is a critical regulator of melanocyte development and acts as a tumor suppressor in melanoma." (PMID 38980592, 2025). "Intriguingly, DAPL1 controls NFATc2 activation to regulate CD8 + T cell exhaustion and responses in chronic infection and cancer, including melanoma." (PMID 38980592, 2025).
oligodendroglioma (1 paper, 2015). A well-differentiated (WHO grade II), diffusely infiltrating neuroglial tumor, typically located in the cerebral hemispheres. "For expression analysis of the DAPL1 locus, we scrutinized expressed sequence tags (EST) and identified three entries [GenBank accession numbers: DA417123 (thalamus), BG818506 (oligodendroglioma), BI016096 (lung tumor)] that suggested alternative splicing of DAPl1 gene products." (PMID 25680934, 2015).
PEComas (1 paper, 2025). "PEComas are also characterized by specific transcriptomic features of the overexpressed DAPL1, MLANA, SULT1C2, GPR143 and CHI3L1 genes, as well as epigenetic features of lysosomal and melanocyte proteins as biomarkers." (PMID 40989692, 2025).
rectal cancer (1 paper, 2022). A primary or metastatic malignant neoplasm that affects the rectum. "Nevertheless, DDC and DAPL1 were positively associated with prognosis and treatment response in rectal cancer." (PMID 36505493, 2022).
retinal degeneration (1 paper, 2024). Degeneration of the retina. "DAPL1 deficiency impairs RPE antioxidant defenses and leads to retinal degeneration." (PMID 39500360, 2024).
retinal detachment (1 paper, 2023). An eye emergency condition which may lead to blindness if left untreated. "For this, we performed subretinal injection of sodium hyaluronate to induce retinal detachment in 8-week-old WT and Dapl1−/− mice and maintained them for 10 days." (PMID 36841807, 2023). "As retinal detachment is one of the causative factors of PVR, we next examined whether DAPL1 deficiency would promote experimental PVR progression." (PMID 36841807, 2023). "Based on fundus photographs and optical coherence tomography (OCT) analyses, ARPE-19+EGFP-injected eyes displayed severe retinal detachment, whereas the ARPE-19 + DAPL1-injected eyes had a much more organized retinal structure." (PMID 36841807, 2023). "After the injection of ARPE-19 + DAPL1 + shP21 cells into the eye, fundus photographs and OCT analyses showed that the injected eyes displayed severe retinal detachment, whereas the eyes injected with ARPE-19 + DAPL1 + shNC cells showed a much more organized retinal structure." (PMID 36841807, 2023).
squamous cell carcinoma (1 paper, 2026). A carcinoma arising from squamous epithelial cells. "We found that a Death associated protein like 1 (DAPL1) was highly expressed in squamous cell carcinoma but not in adenocarcinoma." (PMID 41619017, 2026). "In this study, using RNA-seq data between cancer tissues and adjacent normal tissues of 5 LUAD and 4 LUSC patients, we found that a Death associated protein like 1 (DAPL1) was highly expressed in squamous cell carcinoma but not in adenocarcinoma." (PMID 41619017, 2026).
testicular tumor (1 paper, 2021). "In vitro experiments revealed that DAPL1 overexpression reduced testosterone production in I-10 testicular tumor cells." (PMID 34535743, 2021).
thyroid cancer (1 paper, 2019). "The third variant is an upstream variant in the DAPL1 gene, shown to affect the binding sites of MAZR and Sp1, a potential tumor suppressor in thyroid cancer, by SNPnexus and Segway." (PMID 31614935, 2019).
viral infections (1 paper, 2023). "Dapl1 has been implicated as a critical regulator of CD8 T cell activation and exhaustion, whereas Ifi27l2a is associated with increased susceptibility to bacterial infections and specific viral infections." (PMID 36637239, 2023).
tumor (8 papers, 2019 to 2025). "Real-time PCR analysis of DAPL1 mRNA expression of in UM and paracancerous tissues shows that DAPL1 expression in UM tissues is decreased relative to that in the tumor-adjacent normal tissues." (PMID 38980592, 2025). "DAPL1 (larger diameter) was expressed in the tumor region, and RNASE1 (larger diameter) was expressed in the stromal region." (PMID 39135097, 2024). "Next, to determine whether DAPL1 expression in the testis impacts the steroid synthesis, we used I-10 mouse testis-derived tumor cells to perform a confirmatory in vitro experiment." (PMID 34535743, 2021). "C0 TNFRSF18+ TCs were found in all three tissues, C1 DAPL1+ TCs and C4 MEIS2+ TCs were more common in both normal and tumor tissues overall, and C2 SLC40A1+ TCs were most common in one of the tumor samples." (PMID 40612060, 2025). "We injected DAPL1 overexpressing A375 or MUM-2C cells into the subcutaneous of the 6-week-old BALB/c male nude mice, while equal EGFP overexpressing A375 or MUM-2C cells were used as experimental control, and analyzed tumor progression one month later." (PMID 38980592, 2025). "Other studies have shown that Th17 cells with potent tumor clearing capacity and memory CD8 T cells—with both central memory and stem cell memory characteristics—resulting from lymphatic endothelial cell priming highly up-regulating Dapl1." (PMID 37414528, 2023).
cancer (4 papers, 2022 to 2026). A tumor composed of atypical neoplastic, often pleomorphic cells that invade other tissues. "Finally, DAPL1 is a crucial regulator of CD8 T cell immunity and a potential target for cancer immunotherapy." (PMID 38980592, 2025). "A recent study reported that Dapl1 could facilitate the dysfunction of exhausted CD8+ T cells in chronic infection and cancer, suggesting that hPMSCs might control GVHD through facilitating exhausted T cells via upregulated Dapl1." (PMID 40443676, 2025). "Interestingly, six genes, including ALS2, DAPL1, HS6ST1, IGFBP2, MGC12982, PPIAL4C, are selected in all predictions, i.e., when no samples is removed, or one cancer type data is removed." (PMID 35349572, 2022).
infection (1 paper, 2025). The state of being infected such as from the introduction of a foreign agent such as serum, vaccine, antigenic substance or organism. "Both mRNA and protein levels of DAPL1 were significantly increased in A375, C918 and MuM-2C cells after infection with DAPL1 lentivirus (Lv-DAPL1)." (PMID 38980592, 2025).
retinopathies (1 paper, 2023). "EMT is important for the dysfunction of RPE cells, suggesting that DAPL1-mediated regulation of RPE cell EMT might not only be involved in PVR pathogenesis but could also participate in the regulation of other retinopathies, such as AMD." (PMID 36841807, 2023). "Moreover, NFκB participates in the regulation of multiple biological processes, including immune responses, inflammatory reactions, and apoptosis, which suggests that DAPL1 might have other biological functions in RPE cells and other RPE-dysfunction related retinopathies." (PMID 36841807, 2023).
DAPL1 also shares sentences with these, for which no sentence is quoted: adenocarcinoma (1 paper); allergic disease (1); allergic rhinitis (1); bacterial infections (1); conjunctivitis (1); eosinophilic esophagitis (1); leishmaniasis (1); Leydig cell tumor (1); nevus (1); ovarian carcinoma (1); pituitary adenomas (1); proliferative vitreoretinopathy (1); skin melanoma (1); uveal melanoma (1).